TFR2 (transferrin receptor 2)
Diseases named in the same sentence as TFR2 in open-access papers (continued):
Sharing a sentence is not in itself a finding about the gene and the disease.
tumor (12 papers, 2013 to 2025). "Immunohistochemical analysis revealed a differential pattern of TfR2 expression according to tumor type, with high expression observed in ITSEMs and DSEMs, occasional expression in LCTs, and absence in SCTs." (PMID 39858264, 2025). "The outcomes indicated that there were LTF expression variations in subgroups of tumor stage and N and T stages, SFXN3 in subgroups of tumor stage and M, N, T stage, and TFR2 in subgroups of M, T stage and tumor stage." (PMID 37361050, 2023). "TfR2 is highly expressed in GBM and correlated with tumor grade, but inversely correlated with patient survival and TfR2 silencing in GBM cells inhibited proliferation and cell cycle progression." (PMID 32328462, 2020). "According to QPCR data, the expression profiles of HJV, IRP2, TfR2 and miR-149 genes were dependent on depth of tumor invasion." (PMID 24078156, 2013). "Moreover, previous studies reported frequent TfR2 expression in tumor cell lines, particularly in human ovarian cancer, colon cancer and glioblastoma cell lines." (PMID 39858264, 2025). "Notably, the role of EZH2 involves the epigenetic regulation of TFR2 expression, which further inhibits ferroptosis and enhances drug resistance, a process closely related to cell cycle regulation and tumor proliferation and metastasis." (PMID 40465746, 2025). "TfR2 exhibited variable labeling depending on the tumor microenvironment." (PMID 40427255, 2025). "TFR2, a subtype of TFRs, has been found altered expression in tumor cells." (PMID 37361050, 2023). "Hence, in our system physiologically high expression of TfR and TfR2 can determine high uptake of Tf-conjugates at the organ level, translating into high background for the detection of tumor lesions." (PMID 38117806, 2023). "The phenomenon might be due to the fact that TFR2 sensitizes tumor cells to cell-cycle-specific chemotherapy medications by regulating potential cellular signaling." (PMID 37361050, 2023). "It suggests that expression of TfR2 by tumor cells, along with increased expression of TfR1, may be a strategy for tumor cells to obtain optimal iron input." (PMID 36072803, 2022). "TfR2 was inversely correlated with leukemia tumor burden and overall survival." (PMID 32328462, 2020). "However, in ITSEMs, the elevated TfR2 expression in the absence of TfR1 may also suggest a compensatory mechanism in response to impaired iron metabolism, potentially driving tumor progression and malignancy through atypical activation of TfR2 pathways." (PMID 39858264, 2025). "Overall, we found that at metastatic sites the uptake of labeled transferrin may be variable, and that high physiological expression of TfR and TfR2 by target organs can affect the ability of Tf-conjugates to identify tumor sites, particularly for smaller lesions." (PMID 38117806, 2023). "Compared to that in peritumor tissues, the expression of ferroptosis-inducing genes, including PTGS2, ALOX12, TFR2, and HMOX1, was decreased in tumor tissues, whereas ferroptosis-suppressor genes, including SLC7A11 and GPX4, were increased." (PMID 37554285, 2023). "We investigated the immunolabeling of TfR1, TfR2, and FTH1 in SCO tubules within different microenvironments (immersed in SEMs, immersed in SCTs, or isolated from tumor cells) to provide insights into the possible role of SCO tubules as precancerous testicular conditions." (PMID 40427255, 2025). "Similarly, compared to that in peritumor tissues, the expression of ferroptosis-inducing genes, including PTGS2, HMOX1, TFR2, and NCOA4, was down-regulated in tumor tissues, whereas ferroptosis-suppressor genes SLC7A11 and FTH1 were upregulated." (PMID 37554285, 2023). "The expression of iron-regulatory genes, including hepcidin, TfR2, Tf and IRP1 were significantly down-regulated in the tumorous tissues in comparison to the adjacent non-tumorous liver tissues." (PMID 25476483, 2015).
infection (5 papers, 2010 to 2024). The state of being infected such as from the introduction of a foreign agent such as serum, vaccine, antigenic substance or organism. "The significant increase in TfR1 and TfR2 in wild-type mice during infection was consistent with the need to increase the production of RBCs to cope with Pcc-induced hemolysis." (PMID 38892340, 2024). "Transferrin Receptor 2 null mice are a model of type 3 hereditary hemochromatosis and develop significant iron overload providing increased iron stores at the onset of infection." (PMID 20231891, 2010). "While we did not measure iron absorption and thus iron availability directly during infection in our study, previous studies on Tfr2 dysfunction in mice have demonstrated increased iron absorption through the gut along with increased expression of iron transport genes." (PMID 20231891, 2010). "Fe-supplementation resulted in a significant down-regulation of HFE3 (TFR2), HAMP, FPN1, and LCN2 while BMP6 and FTH1 were significantly up-regulated, compared to the placebo group, at 4 weeks post-infection." (PMID 31382404, 2019).
haematological disorders (2 papers, 2018 to 2020). "Potential therapeutic uses targeting the transferrin-TFR1 axis or TFR2 in hematological disorders are also discussed." (PMID 33352721, 2020).
TFR2 also shares sentences with these, for which no sentence is quoted: acute myeloid leukemia (3 papers); genetic diseases (3); aceruloplasminemia (2); gastric cancer (2); hepatoblastoma (2); hypogonadism (2); liver fibrosis (2); Obesity (2); skin change (2); adenocarcinoma (1); aplastic anemia (1); beta thalassaemia (1); brain tumors (1); colorectal adenoma (1); cystic fibrosis (1); germ cell tumor (1); heart failure (1); hemosiderosis (1); hyperferritinemia (1); iron overload disease (1); liver cancer (1); lung carcinoma (1); lysosomal storage disease (1); metabolic disease (1); metabolism (1); metastatic tumors (1); microcytic anemia (1); sarcoma (1); Sertoli cell tumor (1); Splenomegaly (1).
A further 1 disease shares a sentence with TFR2 in 1 paper.